TRPV1 (transient receptor potential cation channel subfamily V member 1)
Diseases named in the same sentence as TRPV1 in open-access papers (continued):
Sharing a sentence is not in itself a finding about the gene and the disease.
dry mouth (1 paper, 2022). "In this study, we investigated NF distribution, Shh/Gli1 expression, and the role of TRPV1 in dry mouth by using a mouse model of dry mouth syndrome." (PMID 36676024, 2022). "K8 expression was significantly downregulated in the TRPV1-/- dry mouth group (p = 0.003, F = 3.974)." (PMID 36676024, 2022). "Our results indicated that TRPV1 promotes neural regeneration at the taste buds via Shh/Gli1 signaling, thus serving as a useful target for the clinical treatment of dry mouth." (PMID 36676024, 2022). "Thus, TRPV1 positively regulates taste bud cell innervation and differentiation; this finding could be valuable in the clinical treatment of dry mouth-related taste dysfunction." (PMID 36676024, 2022).
Dysmenorrhea (1 paper, 2022). Pain during menstruation that interferes with daily activities. "Studies have shown that the expression of TRPV1 is positively correlated with the degree of chronic pelvic pain in peritoneal lesions and sacral ligament lesions in patients with EMs, and the density of TRPV1 positive nerve fibers positively correlates with the severity of dysmenorrhea." (PMID 35800014, 2022).
Dysphagia (1 paper, 2018). "In addition, in aged people with dysphagia, a TRPV1 or TRPM8 agonist (capsaicin or menthol) applied to the pharynx significantly shortened the latency of the evoked swallowing reflex compared with that for distilled water." (PMID 30567389, 2018).
Ehrlich tumor (1 paper, 2022). "However a possible neuro-immune interaction was insufficient to alter Ehrlich tumor progression in the context of TRPV1 deficiency." (PMID 36138983, 2022). "Our study aimed at investigating the contribution of the primary afferent nociceptive neurons expressing TRPV1 in the nociceptive behaviors triggered upon Ehrlich tumor administration in mice." (PMID 36138983, 2022). "Herein, we investigated the contribution of the transient receptor potential cation channel subfamily V member 1 (TRPV1) in the Ehrlich tumor-induced pain model." (PMID 36138983, 2022). "Intrathecal injection of AMG9810 (TRPV1 antagonist) reduced ongoing Ehrlich tumor-triggered mechanical and thermal hyperalgesia (p < 0.05)." (PMID 36138983, 2022). "Dorsal root ganglia (DRG) neurons from the Ehrlich tumor mice presented higher activity (calcium levels using fluo-4 fluorescent probe) and an increased response to capsaicin (TRPV1 agonist) than the saline-injected animals (p < 0.05)." (PMID 36138983, 2022). "We also addressed whether pharmacological inhibition of TRPV1 could reduce ongoing hyperalgesia triggered by Ehrlich tumors." (PMID 36138983, 2022). "Thus, genetic deletion and pharmacological inhibition demonstrate TRPV1 involvement in pain-like behavior that occurs upon administration of Ehrlich tumor in mice." (PMID 36138983, 2022). "This lack of contribution of TRPV1+ neurons to neuro-immune-cancer interactions supports the rationale that as TRPV1 deficiency reduces pain-like behavior, the major function of this TRP channel in the Ehrlich tumor model is neuronal activation and neurotransmission of nociceptive inputs." (PMID 36138983, 2022). "Therefore, the contribution of TRPV1 to Ehrlich tumor pain behavior was revealed by genetic and pharmacological approaches, thus, supporting the use of this model to investigate TRPV1-targeting therapies for the treatment of cancer pain." (PMID 36138983, 2022). "Therefore, in this study, we evaluated the contribution of TRPV1 to Ehrlich tumor pain." (PMID 36138983, 2022). "Importantly, TRPV1 deficiency did not interfere in Ehrlich tumor growth, as demonstrated by paw thickness and paw weight data." (PMID 36138983, 2022). "Thus, it is also possible that spinal TRPV1+ neuronal afferent terminals contribute to central sensitization in Ehrlich tumor pain via glutamate, although this hypothesis remains to be investigated." (PMID 36138983, 2022). "In conclusion, we demonstrate that TRPV1 is involved in Ehrlich tumor pain-like behavior without interference in tumor progression." (PMID 36138983, 2022). "Corroborating these data, interfering with TRPV1 using genetic and pharmacological approaches reduced Ehrlich tumor-triggered pain-like behavior without affecting tumor growth." (PMID 36138983, 2022). "As far as we know, there is no study investigating central sensitization in the Ehrlich tumor model or whether TRPV1+ primary afferent neurons or afferent terminals of TRPV1+ neurons in the spinal cord contribute to central sensitization in this model." (PMID 36138983, 2022). "Therefore, the present results are consistent with the idea that Ehrlich tumor progression would enhance pain-like behavior over time, and TRPV1 inhibition would reduce pain without a significant role in tumor progression." (PMID 36138983, 2022). "These approaches indicate that in Ehrlich tumors, TRPV1 contributes to pain without affecting tumor progression; thus, therapies targeting TRPV1 could be useful." (PMID 36138983, 2022). "Thus, it is likely that TRPV1+ neurons are not major players in shaping Ehrlich tumor growth." (PMID 36138983, 2022).
eosinophilic esophagitis (1 paper, 2025). Eosinophilic esophagitis (EoE) is a chronic, allergic disease of the esophagus characterized clinically by symptoms of esophageal dysfunction (including vomiting, dysphagia, feeding disorders, food impaction and abdominal pain) which persist after treatment with proton pump inhibitors (PPIs). "In eosinophilic esophagitis (EoE), bursts of refluxed acid flip open epithelial TRPV1 proton sensors, launching an ATP-fuelled NF-κB loop that up-regulates eotaxin-3, weakens tight junctions and locks in eosinophil-driven type-2 inflammation." (PMID 41471371, 2025).
gastroparesis (1 paper, 2020). Paralysis of the muscles of the stomach wall resulting in delayed emptying of the gastric contents into the small intestine. "This is in contrast to the thrombin-astrocyte-glutamate gliotransmission responsible for gastroparesis and earlier reports concerning the involvement of TRPV1 channels in PAR suppression of respiratory control circuits." (PMID 32320636, 2020).
glossitis (1 paper, 2023). Inflammation of the tongue. "Here, we found that a single high-dose of RTX led to substantial and lasting desensitization to a TRPV1 agonist (capsaicin), and when given before radiation, RTX led to reductions in both glossitis severity and RAP behaviors (grooming and nesting)." (PMID 37274254, 2023).
gram-negative bacterial infections (1 paper, 2025). Infections caused by bacteria that show up as pink (negative) when treated by the gram-staining method. "In sensory neurons, TRPV1 may contribute to triggering and regulating innate defense against Gram-negative bacterial infection." (PMID 39859376, 2025).
hematoma (1 paper, 2026). A hematoma is a collection of blood from a vascular structure into an extravascular space. "TRPV1 blockade with CPZ treatment reduced hematoma volume, brain edema, neuronal apoptosis, and improved neurological function, whereas CAP exacerbated injury." (PMID 42007487, 2026).
Hepatitis (1 paper, 2011). Inflammation of the liver. "Use of vanilloid receptorknock-out mice in our study clearly showed that CBD induced suppression ofinflammation in ConA-hepatitis was dependent on TRPV1, so was the induction of MDSCsby CBD in the livers of ConA-injected mice." (PMID 21483776, 2011). "Importantly, we haveidentified a novel pathway through which CBD suppresses hepatitis involving theinduction of MDSCs in liver following activation of vanilloid receptor, TRPV1." (PMID 21483776, 2011). "Moreover, CBD was found to induce MDSCs following activationof TRPV1 inasmuch as, CBD failed to trigger MDSCs in the livers of TRPV1 deficientmice and failed to protect them from hepatitis." (PMID 21483776, 2011).
Hyperoxaluria (1 paper, 2021). Increased excretion of oxalates in the urine. "In the 14 day treated kidneys, TRPV1 inhibition by Capz or SB significantly reduced Nox4 expression caused by hyperoxaluria." (PMID 34201387, 2021). "Chronic delivery of two specific TRPV1 blockers, Capz and SB, for 7 and 14 days via subcutaneous mini-osmotic pump significantly attenuated hyperoxaluria-induced renal hypertrophy (as the ratio of kidney to body weight)." (PMID 34201387, 2021). "Blockade of TRPV1 mitigates the detrimental effect of inflammation-induced tubular damage in both in vitro and in vivo models of hyperoxaluria, indicating a potential role of TRPV1 antagonism in the treatment of oxalate nephropathy." (PMID 34201387, 2021). "To confirm the in vitro observations of tubular inflammation, we then investigated the pro-inflammatory role of the ALOX12/TRPV1 pathway in the in vivo rat model of hyperoxaluria." (PMID 34201387, 2021). "TRPV1 hyperfunction in oxalate-mediated nephropathy is further evidenced by in vivo observations showing that chronic TRPV1 inhibition markedly reduced hyperoxaluria-induced tubular damage and CaOx crystal formation via inflammation." (PMID 34201387, 2021). "Since inflammation plays an important role in the disease progression of nephrolithiasis, we hypothesized that the 12(S)-HETE/TRPV1 pathway would play a role in hyperoxaluria-induced tubular damage and CaOx formation." (PMID 34201387, 2021). "Interestingly, inhibition of TRPV1 attenuates oxalate- or hyperoxaluria-induced NLRP3 upregulation." (PMID 34201387, 2021). "Here, we tested whether TRPV1 plays a role in hyperoxaluria-induced renal inflammation." (PMID 34201387, 2021). "Hyperoxaluria-induced renal NLRP3 upregulation and increased caspase-1 activity and renal content of IL-1β in HP kidneys were reduced by TRPV1 inhibition." (PMID 34201387, 2021). "Chronic TRPV1 inhibition did not affect hyperoxaluria and urinary supersaturation, but markedly reduced tubular damage and calcium oxalate crystal deposition by lowering oxidative stress and inflammatory signaling." (PMID 34201387, 2021). "Because there were parallel changes in TRPV1, ALOX12, and NLRP3 expression as well as caspase-1 activation and IL-1β formation in HP kidneys, we examined whether inhibition of TRPV1 would ameliorate hyperoxaluria-induced renal inflammation and tubular injury." (PMID 34201387, 2021).
hyperthyroidism (1 paper, 2017). Overactivity of the thyroid gland resulting in overproduction of thyroid hormone and increased metabolic rate. "This anti-hyperthyroidism effect of MOK pharmacopuncture is thought to be related to the control of thermo-regulating protein TRPV1 in DRG and brain." (PMID 29246135, 2017). "Our results indicate that MOK pharmacopuncture regulates heat intolerance in hyperthyroidism through decreasing the body temperature with downregulation of the thermo-regulator TRPV1 expression in DRG and brain tissues." (PMID 29246135, 2017). "In our study, MOK pharmacopuncture exhibited a thermoregulatory property through downregulation of the TRPV1 expression in DRG and brain tissues of LT4-induced hyperthyroidism rats." (PMID 29246135, 2017). "In the expression of TRPV1, the treatment of MOK pharmacopuncture in hyperthyroidism was significantly decreased in both DRG and brain tissues in a dose-dependent manner." (PMID 29246135, 2017).
Impaired glucose tolerance (1 paper, 2019). An abnormal resistance to glucose, i.e., a reduction in the ability to maintain glucose levels in the blood stream within normal limits following oral or intravenous administration of glucose. "First, we induced impaired glucose tolerance in mice by HFD and asked the question whether this could be prevented by the genetic inactivation of TRPV1 (Trpv1−/− mice)." (PMID 31344877, 2019).
influenza (1 paper, 2023). An acute viral infection of the respiratory tract, occurring in isolated cases, in epidemics, or in pandemics; it is caused by serologically different strains of viruses (influenzaviruses) designated A, B, and C, has a 3-day incubation period, and usually lasts for 3 to 10 days. "However, influenza-induced sickness behaviour was normal in Trpv1-IRES-cre; Ptger3flox mice, and furthermore, GABRA1 neurons are predominantly Trpv1-negative." (PMID 36890237, 2023).
intestinal cancer (1 paper, 2020). "Furthermore, TRPV1 depletion causes the spontaneous growth of intestinal tumours, highlighting the tumour suppressor function of TRPV1 in intestinal cancer." (PMID 32575381, 2020).
Intestinal Infection (1 paper, 2012). "In the present study, on the basis of using MCs deficient rats, we attempted to identify colonic (PAR2 and NGF) and peripheral sensory neuronic alterations (pERK1/2 and TRPV1) that can be involved in the visceral hyperalgesia triggered by both intestinal infection and stress." (PMID 22529522, 2012).
intracerebral hemorrhage (1 paper, 2026). A cerebrovascular disorder characterized by bleeding into one or both cerebral hemispheres including the basal ganglia and the cerebral cortex. "Although TRPV1 activation contributes to intracerebral hemorrhage (ICH) pathology, its microglia-specific role and underlying mechanisms remain poorly defined." (PMID 42007487, 2026).
invasive ductal carcinoma (1 paper, 2023). "In invasive ductal carcinoma, three distinct TRPV1 staining patterns have been described using the Abcam (Cambridge, MA, USA) anti-TRPV1 antibody: “classical” (diffuse staining in membrane and cytology), “non-classical” (endoplasmic reticulum/Golgi pattern), and “mixed”." (PMID 37240443, 2023).
irritation (1 paper, 2023). "The regulation of several symptoms, including pain, inflammation, hyperalgesia, and skin irritation, depends heavily on the expression and activation of TRPV1." (PMID 36827162, 2023).
ischemic cardiomyopathy (1 paper, 2022). Ischemic cardiomyopathy is a cardiomyopathy in which a weakness in the muscle of the heart due to inadequate oxygen delivery to the myocardium with coronary artery disease being the most common cause. "Our observations suggest that rs224534 the common missense variant of TRPV1 is associated with the prognosis of ischemic cardiomyopathy in the Chinese Han population, suggesting it may help identify newly predicted targets for ICM." (PMID 35905222, 2022).
ischemic disease (1 paper, 2020). Lack of blood supply to an area of the body, resulting in impairment of tissue oxygenation. "Taken together, these observations suggest that TRPV1 represents a useful target in the treatment of ischemic diseases." (PMID 32471282, 2020).
keratitis (1 paper, 2019). A corneal disease that is characterized by inflammation of the cornea. "Decreased expression of neuron-selective transient receptor potential vanilloid type 1 (TRPV1) in the trigeminal ganglia neurons was also demonstrated in rats treated with fucoxanthin after UVB-induced keratitis." (PMID 30841522, 2019).
lactic acidosis (1 paper, 2016). Metabolic acidosis characterized by the accumulation of lactate in the body. "Taken together, our data demonstrate for the first time that TRPV1 distinguishes between acidosis as opposed to lactic acidosis, and postulates a yet unknown role for LA as an endogenous regulator of TRPV1." (PMID 27827430, 2016).
left ventricular hypertrophy (1 paper, 2014). Enlargement of the LEFT VENTRICLE of the heart. "In our study, protein expression of PPAR-δ was decreased in both WT and TRPV1−/− mice in the HS group, which eventually exhibited notable left ventricular hypertrophy." (PMID 25152753, 2014).
lens diseases (1 paper, 2022). "These suggest that TRPV1 is a potential therapeutic target in hyperglycemic-related lens diseases." (PMID 36430438, 2022). "Nevertheless, the functional role of TRPV1 in hyperglycemic-related lens disease remains unclear." (PMID 36430438, 2022).
lichen sclerosus (1 paper, 2022). "Taking all of this into account, TRPV1 could have a role in the pathogenesis of lichen sclerosus." (PMID 36551194, 2022).
liver cirrhosis (1 paper, 2024). "The downregulation of Transient Receptor Potential Vanilloid 1 (TRPV1) expression in liver cirrhosis tissue, caused by a variety of etiologies, has been observed." (PMID 38255767, 2024). "This study demonstrates a significant decrease in TRPV1 expression in liver cirrhosis tissue due to diverse etiologies." (PMID 38255767, 2024).
measles (1 paper, 2020). A highly contagious viral infection caused by the measles virus. "TRP channels have primarily been characterized in infections with respiratory viruses such as rhinovirus, measles, and respiratory syncytial virus which have been shown to upregulate TRPV1 causing hypersensitization to cough and promotion of airborne viral dissemination." (PMID 32231022, 2020).
meningioma (1 paper, 2024). A generally slow growing tumor attached to the dura mater. "Moreover, expression levels of Beclin, LC3B, HST1, TRPV1, TRPA1, Nrf2, and DDX3X did not associate with OS of meningioma patients (p>0.05)." (PMID 38758750, 2024).
meningitis (1 paper, 2025). A disorder characterized by acute inflammation of the meninges of the brain and/or spinal cord. "Although all three strains used in this study can cause meningitis in humans, serotype 6A was suitable for the model for studying TRPV1-mediated nose-to-brain invasion." (PMID 40823821, 2025). "Steroids are used for an effective treatment for meningitis, because they may inhibit the trigeminal TRPV1-mediated inflammatory response." (PMID 40823821, 2025).
mental disorder (1 paper, 2021). A disease that has its basis in the disruption of mental process. "Furthermore, it seems necessary to study how the interaction between TRPV1 and naringin affects mental disorders and neurodegenerative diseases." (PMID 35052566, 2021).
mesothelioma (1 paper, 2022). A usually malignant and aggressive neoplasm of the mesothelium which is often associated with exposure to asbestos. "CBD and CBG increased mRNA expression of transient receptor potential vanilloid type 1 (TRPV1) in all mesothelioma cell lines, except in CBD-treated H2452 cells." (PMID 35954477, 2022).
metabolic bone disorder (1 paper, 2021). A group of disorders that affect the bones secondary to increased levels of minerals or deficient levels of minerals such as calcium, magnesium, phosphorus, and vitamin D. Representative examples are osteomalacia, osteoporosis, and Paget disease. "Considering these observations, the administration of compounds activating CB2 receptors and/or antagonizing/desensitizing TRPV1 channels might have potential benefits for managing metabolic bone disorders in which an imbalance of coupling (i.e., OB/OC activity) is observed." (PMID 34576321, 2021).
Microscopic hematuria (1 paper, 2022). Microscopic hematuria detected by dipstick or microscopic examination of the urine. "Bladder biopsies from individuals with PBS who met the National Institute for Diabetes and Digestive and Kidney Diseases (NIDDK) research criteria for IC showed increased TRPV1 immunoreactivity within the nerve fibers compared with biopsies from individuals with asymptomatic microscopic hematuria." (PMID 36135835, 2022).
myofascial pain syndrome (1 paper, 2025). Muscular pain in numerous body regions that can be reproduced by pressure on trigger points, localized hardenings in skeletal muscle tissue. "Nonetheless, our study affirms that skeletal muscle TRPV1 may serve as a potential therapeutic target for myofascial pain syndrome, with this process likely occurring through the reduction of mitochondrial damage." (PMID 40698665, 2025). "The objective of this study is to elucidate the therapeutic mechanisms underlying silver needle thermal therapy (SNT) in alleviating skeletal muscle mitochondrial damage in a rat model of myofascial pain syndrome (MPS), with particular emphasis on its regulatory role concerning TRPV1/CaMKII." (PMID 40698665, 2025).